CRABP1 (cellular retinoic acid binding protein 1)
Description:
Cytosolic CRABPs may regulate the access of retinoic acid to the nuclear retinoic acid receptors.
Synonyms: CRABP-I; RBP5; CRABP; CRABPI
Tractability: Small molecule: a structure with a bound ligand is known. PROTAC: it is named in the literature on targeted protein degradation; ubiquitination databases record sites on it; its protein half-life has been measured.
Target class: Fatty acid binding protein family; Auxiliary transport protein
Gene: Protein-coding gene on chromosome 15 (78,340,260 to 78,348,250, forward strand). Ensembl gene ENSG00000166426.
Subcellular location: Cytoplasm
Pathways (Reactome):
Signal Transduction: RA biosynthesis pathway
Gene Ontology:
Molecular function: protein binding; fatty acid binding; retinoic acid binding; retinoid binding; lipid binding
Biological process: fatty acid transport; signal transduction
Cellular component: cytosol; nucleus; cytoplasm
Genetic constraint (gnomAD): Loss-of-function variants: 9 observed, 15.49 expected, observed/expected ratio (o/e) 0.58, 90% interval 0.35 to 1.01. The upper end of that interval is the gene's LOEUF score, 1.01, which puts it in group 4 of 6, group 1 being the genes least tolerant of losing a copy. Missense variants: 155 observed, 184.42 expected, observed/expected ratio (o/e) 0.84, 90% interval 0.74 to 0.96. Synonymous variants: 72 observed, 70.27 expected, observed/expected ratio (o/e) 1.02, 90% interval 0.85 to 1.25.
Homologues: Orthologues: chimpanzee CRABP1 (100% identical), dog CRABP1 (100% identical), pig CRABP1 (100% identical), mouse Crabp1 (99% identical), rabbit CRABP1 (99% identical), rat Crabp1 (99% identical), guinea pig CRABP1 (98% identical), macaque CRABP1 (90% identical), zebrafish crabp1a (85% identical), zebrafish crabp1b (85% identical), tropical clawed frog crabp1 (82% identical), Caenorhabditis elegans lbp-7 (32% identical), and 2 more. Paralogues in human: CRABP2 (76% identical), FABP3 (39% identical), FABP7 (37% identical), PMP2 (37% identical), RBP1 (36% identical), FABP4 (34% identical), FABP9 (34% identical), FABP2 (33% identical), RBP7 (33% identical), FABP12 (31% identical), FABP5 (31% identical), RBP2 (29% identical), and 3 more.
Diseases named in the same sentence as CRABP1 in open-access papers:
CRABP1 is named in the same sentence as 107 diseases in open-access papers, as found by Europe PMC text mining. Sharing a sentence is not in itself a finding about the gene and the disease. The quoted sentences say what the papers report.
breast carcinoma (8 papers, 2014 to 2023). "Elevated CRABP1 levels are associated with poor patient prognosis, high Ki67 immunoreactivity and high tumor grade in breast cancer." (PMID 26142905, 2015). "Here, we report the expression, clinicopathological association and function of CRABP1 in breast cancer." (PMID 26142905, 2015). "In agreement with a pro-carcinogenic role for CRABP1, we found an association between CRABP1 expression and worse clinical outcomes in breast cancer using both gene profiling and TMA analysis." (PMID 26142905, 2015). "To further explore the mechanism involved in CRABP1/RA-mediated effects in breast cancer cells, we examined the expression of critical genes implicated in RA synthesis, trafficking, metabolism and action upon CRABP1 manipulation and RA treatment." (PMID 26142905, 2015). "Crabp1 was also expressed within the tumor-associated stroma of patient-derived primary human breast cancer tissues." (PMID 24405573, 2014). "Another recent study identified CRABP1 as the third key player that potentially influences the breast cancer cell response to ATRA." (PMID 30384831, 2018). "We postulate that CRABP1 plays a key role in attenuating RA activity in breast cancer cells, with high levels of CRABP1 reducing availability of RA in the nucleus." (PMID 26142905, 2015). "Our data indicate that CRABP1 is an adverse prognostic factor and a potent inhibitor of RA action in breast cancer which functions by sequestering RA in the cytoplasm rather than by enhancing RA metabolism." (PMID 26142905, 2015). "These combined data suggest the presence of a CRABP1-AP-2α-CRABP2 axis which modulates RA action in breast cancer cells." (PMID 26142905, 2015). "CRABP1 is an adverse factor for clinical outcome in triple-negative breast cancer and a potent inhibitor of RA signalling in breast cancer cells." (PMID 26142905, 2015). "We demonstrate that CRABP1 expression attenuates RA-induced cell growth arrest and inhibits RA signalling in breast cancer cells by sequestering RA in the cytoplasm." (PMID 26142905, 2015). "It is noteworthy that estrogen signaling has been linked to the regulation of DNA methylation, perhaps explaining to some extent the reduced expression of CRABP1 observed in ER+ compared to ER- breast cancers." (PMID 26142905, 2015). "DNA methylation-mediated silencing of CRABP1 has been observed in a subset of breast carcinoma tissues." (PMID 26142905, 2015). "In this study, we identify a third RA-binding protein, CRABP1, as an inhibitor of RA action and an adverse factor for clinical outcome in breast cancer." (PMID 26142905, 2015). "In addition, several retinoic acid transport proteins have been found to correlate with increase pancreatic cancer cell motility and invasion, including CRABP2 and FABP5, while CRABP1 correlates with worse prognosis in breast cancer." (PMID 37130839, 2023). "And CRABP1 was methylated in the majority of epithelial breast cancer cell lines." (PMID 31419991, 2019). "CRABP1 can promote the development of prostate cancer and breast cancer." (PMID 31419991, 2019). "So we hypothesized whether the biological function of CRABP2 in regulating breast cancer was related to CRABP1." (PMID 31419991, 2019). "We also screened a panel of 11 breast cancer cell lines for CRABP1 and CRABP2 expression." (PMID 26142905, 2015). "We propose that CRABP1 may serve as a biomarker to predict RA response and a target to optimize the efficacy of RA in breast cancer treatment." (PMID 26142905, 2015). "In light of CRABP1’s proposed role in attenuating RA activity by enhancing RA metabolism, expression of CRABP1 in breast cancer could have important implications for RA response." (PMID 26142905, 2015). "Elevated levels of CRABP1 may lead to RA resistance in breast cancer cells through sequestration of RA in the cytoplasm thereby preventing RA-mediated induction of RAR." (PMID 26142905, 2015).
breast carcinoma (continued). "To investigate whether there is any association between the subcellular distribution of CRABP1 and 2 and clinical outcomes, we conducted immunohistochemical analysis of a TMA containing primary tumor samples from 120 breast cancer patients." (PMID 26142905, 2015). "Again, these results suggest opposing roles for CRABP1 and CRABP2 in breast cancer clinical outcomes." (PMID 26142905, 2015). "Our results suggest that CRABP1, in addition to the previously identified FABP5 and CRABP2, is a key factor regulating breast cancer cell response to RA." (PMID 26142905, 2015). "In this study, we found that CRABP1 and CRABP2 have inverse expression patterns in breast tumors and play an opposing role in the mediation of RA action in breast cancer cells." (PMID 26142905, 2015). "Intriguingly, CRABP1 not only inversely regulates CRABP2 expression, but also affects nuclear translocation of CRABP2 in breast cancer cells." (PMID 26142905, 2015). "Our data indicate that CRABP1, in conjunction with previously identified CRABP2 and FABP5, plays a key role in breast cancer cell response to RA." (PMID 26142905, 2015). "That result indicated that the effect of CRABP2 on invasion and metastasis through Hippo pathway in breast cancer was independent of CRABP1." (PMID 31419991, 2019). "CRABP1, a third member of the RA-binding protein family, has not previously been investigated as a possible mediator of RA action in breast cancer." (PMID 26142905, 2015). "To further understand the opposing roles of CRABP1 and CRABP2 in breast cancer progression, we immunostained our breast cancer TMA with Ki67, a cell proliferation marker, and examined its correlation with CRABP protein levels." (PMID 26142905, 2015). "Prior to this study, the expression and prognostic significance of CRABP1 in breast cancer had not been investigated." (PMID 26142905, 2015). "Thus, both CRABP1 and FABP5 represent potential therapeutic targets to overcome RA resistance in breast cancer." (PMID 26142905, 2015). "The previous results show that CRABP1 and CRABP2 may have different effects on breast cancer." (PMID 31419991, 2019). "CRABP1 and FABP5 co-expression may serve as a predictive biomarker of ATRA resistance in this tumor type, and the downregulation may be a key step in (re)sensitizing breast carcinoma cells to retinoid therapy." (PMID 30384831, 2018).
adenoma (6 papers, 2008 to 2021). A neoplasm arising from the epithelium. "In the first pathway, adenoma formation occurs in an MMR-proficient background, and carcinogenesis is characterized by APC and/or KRAS mutation and IGF2, NEUROG1, CDK2A, and/or CRABP1 hypermethylation." (PMID 34201893, 2021). "A recent study showed significantly elevated methylation levels of CRABP1 in MMR-proficient adenomas of LS patients." (PMID 34201893, 2021). "In sebaceous tumours, CRABP1 was found more expressed in adenomas than in carcinomas and in early well-differentiated porocarcinoma than in more aggressive and progressed porocarcinoma." (PMID 31065284, 2019). "Quantitative RT-PCR analysis on new follicular samples confirmed the upregulation of CRABP1 expression in all the adenomas as compared to follicular carcinomas." (PMID 19893615, 2009). "Moreover, MMR-deficient adenomas with a high grade of dysplasia revealed hypermethylation in four other genes, IGF2, CRABP1, NEUROG1, and CDKN2A." (PMID 34201893, 2021). "In sebaceous tumours, CRABP1 was expressed in adenomas more than carcinomas and in early well-differentiated porocarcinoma more than in more aggressive and progressed porocarcinoma indicating a role in the formation and the transition of these tumours rather than in progression and invasion." (PMID 31065284, 2019). "We subsequently confirmed their modulation at the protein level by immunohistochemistry: cytoplasmic staining of CRABP1 was increased in follicular adenoma, and FABP4 expression was reduced in adenoma and further reduced in carcinoma." (PMID 29535811, 2018). "ADAMTS1, CDKN2A, CRABP1, MLH1, NR3C1, RUNX3, and SCGB3A1 showed increasing methylation frequencies from adenomas to carcinomas, while HOXA9, MAL, and MGMT displayed overall equal methylation frequencies in all tumor subgroups." (PMID 19117505, 2008). "Moreover, Maki-Nevala and colleagues found higher methylation levels in four CIMP marker genes, namely NEUROG1, CDKN2A, IGF2, and CRABP1, in MMR-proficient adenomas compared to normal mucosa." (PMID 34201893, 2021). "The prospective LS series revealed increased methylation in adenomas and carcinomas vs. normal colonic mucosa for the CIMP markers IGF2, NEUROG1, and CRABP1 (p values mostly non-significant due to small numbers of specimens)." (PMID 26203307, 2015).
neuroblastoma (6 papers, 2005 to 2022). Neuroblastoma (NB) is the most common solid, extracranial childhood tumor. "As it is known that CRABP1 sequesters RA in the cytoplasm, its elevated expression in neuroblastoma could cause RA resistance by limiting RA access to the nucleus mediated by its binding to CRABP2." (PMID 35490242, 2022). "Knockdown and overexpression, respectively, of either p75NTR or CRABP1 were effected in neuroblastoma cell lines using standard techniques." (PMID 26843908, 2016). "While protein content of CRABP1 correlated roughly with that of p75NTR in the three neuroblastoid or epithelioid human neuroblastoma cell lines studied, manipulation of p75NTR expression resulted in cell line-dependent, variable change in CRABP1 expression." (PMID 26843908, 2016). "Our results demonstrate neuroblastoma cell line-dependence of the effects of manipulation of p75NTR expression on CRABP1 expression and the effects of CRABP1 expression on fenretinide-induced cell death." (PMID 26843908, 2016). "Commensurate with the coordinate variation of p75NTR and CRABP1 in native neuroblastoma cells, SH-EP1 cells induced to overexpress p75NTR (p75OE cells) had higher levels of CRABP1 protein than mock-transfected control cells." (PMID 26843908, 2016). "The fact that p75NTR and CRABP1 expression differentially affect one another and the impact of treatment with fenretinide in different neuroblastomas makes p75NTR or CRABP1, at best, complex biomarkers for likely responsiveness to that drug." (PMID 26843908, 2016). "CRABP1 protein concentration does covary with p75NTR protein concentration in native human neuroblastoma cell lines." (PMID 26843908, 2016). "We therefore examined the effects of CRABP1 expression on p75NTR expression and fenretinide efficacy in neuroblastoid human neuroblastoma cells." (PMID 26843908, 2016). "The effects of manipulation of p75NTR expression on CRABP1 expression and the effects of CRABP1 expression on fenretinide efficacy are therefore neuroblastoma cell line-dependent." (PMID 26843908, 2016). "In this study, we found that neuroblastoma had the highest CRABP1 expression." (PMID 35490242, 2022). "Therefore, we tested how specific MYCN inhibition by BGA002 and RA treatment affected CRABP1/2 expression in neuroblastoma cell lines." (PMID 35490242, 2022). "The presently described studies test the hypothesis that p75NTR-induced potentiation of the effects of fenretinide on neuroblastoma cells occurs through regulation by p75NTR of the expression of the cellular retinoic acid binding protein I (CRABP1)." (PMID 26843908, 2016). "Demonstration of coordinate regulation of p75NTR and CRABP1, and CRABP1 knockdown-induced decrease in fenretinide efficacy in SH-EP1 cells caused us to examine whether these effects are also seen in the SK-N-AS epithelioid human neuroblastoma cell line." (PMID 26843908, 2016). "In this context, it is of relevance our finding that only the combined BGA002-RA treatment induced a concomitant downregulation of CRABP1 and upregulation of CRABP2 expression, reverting the CRABP1/2 balance in neuroblastoma cells." (PMID 35490242, 2022).
ovarian carcinoma (6 papers, 2007 to 2024). A malignant neoplasm originating from the surface ovarian epithelium. "Epigenetic studies in which promoter methylation status of several genes in primary ovarian carcinomas and their in vitro models were assayed showed that the Crabp1 gene promoter and the CpG islands of its coding region were hypermethylated – indicating a loss of Crabp1 expression." (PMID 26935534, 2016). "By DNA methylation analysis, CRABP1 was identified as a hypermethylated target gene of ovarian cancer." (PMID 36419120, 2022). "“Given the ability of atRA and compounds 3 and 4 to induce apoptosis in animal cancer cell line context, we surveyed several additional cell lines and found that CRABP1 expression was lost in human ovarian cancer cell line A2780 and mouse pancreatic ductal carcinoma cell line KPC”." (PMID 27435798, 2016). "Given the ability of atRA and compounds 3 and 4 to induce apoptosis in animal cancer cell line context, we surveyed several human cell lines and found that CRABP1 expression was lost in human ovarian cancer cell line A2780 and human pancreatic ductal carcinoma cell line KPC." (PMID 26935534, 2016). "The effect of DIG-MSK was also evident on the loading of Sp1 on the other gene promoters: XIAP whose down-regulation can induce cell death, CRABP1, a gene involved in the development of ovarian carcinoma, and MDK that is a marker in ovarian cancer." (PMID 25110883, 2014). "CDH13, CRABP1, HOXA9, and SCGB3A1 were subjected to direct bisulphite sequencing in the four ovarian carcinoma cell lines." (PMID 17623056, 2007). "CpG island promoter hypermethylation of tumour suppressor genes is a common event in primary ovarian carcinomas and cell lines, and HOXA9, HOXB5, SCGB3A1, and CRABP1, represent novel hypermethylated target genes in this disease." (PMID 17623056, 2007). "APC, CDH13, CRABP1, HOXA9, HOXB5, RASSF1A, and SCGB3A1 were found to be hypermethylated both in the primary tumours and in ovarian cancer cell lines, whereas ADAMTS1 and MGMT were hypermethylated only among cell lines." (PMID 17623056, 2007). "The investigated gene promoters were chosen from loci previously reported to be methylated in ovarian cancer (n = 7; APC, CDH13, MGMT, MLH1, p14ARF, p16INK4a, RASSF1A) and from loci methylated in other tumour types (n = 6; ADAMTS1, CRABP1, HOXA9, HOXB5, NR3C1, SCGB3A1)." (PMID 17623056, 2007). "High levels of CRABP1 were detected in NBL but not in NSCLC, ovarian cancer, and glioblastoma." (PMID 36419120, 2022).
colorectal cancer (5 papers, 2007 to 2019). A primary or metastatic malignant neoplasm that affects the colon or rectum. "We obtained 401 colorectal cancer specimens and successfully quantified DNA methylation in eight CIMP-specific gene promoters (CACNA1G, CDKN2A, CRABP1, IGF2, MLH1, NEUROG1, RUNX3, and SOCS1) using MethyLight technology." (PMID 31690257, 2019). "We obtained 920 colorectal cancer specimens and quantified DNA methylation in the 8 CIMP-specific gene promoters (CACNA1G, CDKN2A, CRABP1, IGF2, MLH1, NEUROG1, RUNX3 and SOCS1) by MethyLight technology." (PMID 17474983, 2007). "Recently, we showed that promoter hypermethylation of ADAMTS1, CRABP1, and NR3C1 was frequent among colorectal carcinomas and cell lines and to a certain extent in colorectal adenomas." (PMID 17623056, 2007). "Utilizing MethyLight technology (real-time PCR), we quantified DNA methylation in 8 CIMP-specific promoters {CACNA1G, CDKN2A (p16), CRABP1, IGF2, MLH1, NEUROG1, RUNX3 and SOCS1} in 758 non-MSI-high colorectal cancers obtained from two large prospective cohorts." (PMID 17474983, 2007).
thyroid tumor (5 papers, 2009 to 2022). A benign or malignant neoplasm affecting the thyroid gland. "Among these, metallophosphoesterase domain containing 2 (MPPED2) and cellular retinoic acid-binding protein 1 (CRABP1) under-expression have already been observed in thyroid tumours." (PMID 19809427, 2009). "We conclude that the underexpression of CRABP1 and the overexpression of LCN2 may be useful diagnostic biomarkers in thyroid tumours with questionable malignity, and the overexpression of LCN2 and C1QL1 may be useful for prognostic purposes." (PMID 29321030, 2018). "We also integrated differentially downregulated DEGs from the datasets and identified six downregulated DEGs, namely, MPPED2, TNFRSF11B, FHL1, CRABP1, MATN2, and TFF3, collectively known as thyroid tumor-downregulated genes (TTDGs)." (PMID 35990603, 2022). "As for the CRABP1 paralog FABP4, its expression in thyroid tumors seems to be inversely correlated to the malignancy or aggressiveness of the tumors and has been used in general classifiers proposed to discriminate malignant from benign thyroid tissues." (PMID 29535811, 2018).
colon cancer (4 papers, 2011 to 2017). "Among the group of the most consistently hypermethylated genes in both human colon cancer and mouse intestinal adenoma (48 genes), we found Cdh4, Crabp1, Crmp1, Dbc1, Duox1, Grm7, Hand1, Hs3st2, Pcdh17 and Pdpn, which have previously been suggested as cancer biomarkers." (PMID 23408899, 2013). "Highly connected biomarkers (with degree centrality) were BRAF mutation (0.19) and methylation-related markers including CDKN2A (0.17), IGF2 (0.17), RUNX3 (0.17), CACNA1G (0.15), CRABP1 (0.15), and NEUROG1 (0.15) in the proximal colon cancer network." (PMID 28623901, 2017). "In total, 31 CpG sites, located in 8 different genes (RUNX3, MLH1, NEUROG1, CDKN2A, IGF2, CRABP1, SOCS1 and CACNA1G) were investigated in 64 distinct colon cancers and 2 colon cancer cell lines." (PMID 24466191, 2014).